ANO9 (anoctamin 9)
Description:
PKA-activated nonselective cation channel. Discriminates poorly among cations but is more permeable to Ca(2+) ions than to monovalent cations (By similarity). Acts as a calcium-activated calcium permeable channel which may operate as a endoplasmic reticulum (ER) Ca(2+)-leak channel, reducing the loading of the ER Ca(2+) store. Regulates intracellular Ca2+ signals, ion channel activity, and cytokine release in the renal tissue. Plays an important role in olfaction, amplifying cAMP-evoked cyclic nucleotide-gated (CNG) channel currents in the olfactory sensory neurons (By similarity). Has calcium-dependent phospholipid scramblase activity; scrambles phosphatidylserine, phosphatidylcholine and galactosylceramide (By similarity). Does not exhibit calcium-activated chloride channel (CaCC) activity. Can inhibit the activity of ANO1.
Synonyms: PIG5; TMEM16J; TP53I5
Tractability: Antibody: UniProt places it where antibodies can reach, with high confidence; its Gene Ontology location is reachable by antibodies, with high confidence; UniProt predicts a signal peptide or a membrane-spanning region.
Gene: Protein-coding gene on chromosome 11 (417,921 to 442,072, reverse strand). Ensembl gene ENSG00000185101.
Subcellular location: Cell membrane; Endoplasmic reticulum
Subcellular location (Human Protein Atlas): Golgi apparatus
Pathways (Reactome):
Disease: Induction of Cell-Cell Fusion
Transport of small molecules: Stimuli-sensing channels
Gene Ontology:
Molecular function: calcium channel activity; channel activity; chloride channel inhibitor activity; intracellularly calcium-gated chloride channel activity; protein binding; chloride channel activity; phospholipid scramblase activity; protein dimerization activity
Biological process: chloride transmembrane transport; calcium activated phosphatidylserine scrambling; monoatomic ion transmembrane transport; calcium ion transmembrane transport; sensory perception of smell
Cellular component: endoplasmic reticulum; plasma membrane
Genetic constraint (gnomAD): Loss-of-function variants: 80 observed, 94.27 expected, observed/expected ratio (o/e) 0.85, 90% interval 0.71 to 1.02. The upper end of that interval is the gene's LOEUF score, 1.02, which puts it in group 4 of 6, group 1 being the genes least tolerant of losing a copy. Missense variants: 1,064 observed, 1,054 expected, observed/expected ratio (o/e) 1.01, 90% interval 0.96 to 1.06. Synonymous variants: 473 observed, 425.51 expected, observed/expected ratio (o/e) 1.11, 90% interval 1.03 to 1.2.
Homologues: Orthologues: macaque ANO9 (93% identical), chimpanzee ANO9 (93% identical), pig ANO9 (75% identical), dog ANO9 (74% identical), guinea pig ANO9 (74% identical), rat Ano9 (73% identical), mouse Ano9 (71% identical), zebrafish ano9b (45% identical), zebrafish ano9a (44% identical). Paralogues in human: ANO4 (38% identical), ANO3 (37% identical), ANO2 (34% identical), ANO5 (33% identical), ANO1 (32% identical), ANO7 (32% identical), ANO6 (31% identical), ANO8 (21% identical), ANO10 (18% identical), PPP1R7 (9% identical).
Diseases named in the same sentence as ANO9 in open-access papers:
ANO9 is named in the same sentence as 14 diseases in open-access papers, as found by Europe PMC text mining. Sharing a sentence is not in itself a finding about the gene and the disease. The quoted sentences say what the papers report.
pancreatic cancer (6 papers, 2019 to 2022). "The scramblase is overexpressed in pancreatic cancer cells, and high ANO9 expression is a poor prognostic factor in patients with pancreatic cancer." (PMID 35207044, 2022). "ANO9 has been studied for its role in pancreatic cancer where, like ANO1, it binds to and activates EGFR and downstream ERK signalling." (PMID 36497413, 2022). "ANO9 was highly expressed in pancreatic cancer and promoted the metastasis of pancreatic cancer cells by increasing epidermal growth factor receptor expression." (PMID 34238763, 2021). "Furthermore, ANO9 knockdown sensitises pancreatic cancer cells to EGFR-targeted treatment with erlotinib." (PMID 36497413, 2022). "Moreover, ANO9 has been suggested as clinically useful prognostic marker for pancreatic cancer and a potential therapeutic target." (PMID 35207044, 2022). "If overexpression of ANO9 in pancreatic cancer cells would additionally correlate with increased ADAM sheddase activity and increased release of EGFR ligands, accelerated tumor progression and metastasis could be the detrimental consequences." (PMID 35207044, 2022). "For ANO9 (TMEM16J) an inverse correlation of expression and progression of colorectal cancer was described, while it may also promote pancreatic cancer." (PMID 30893776, 2019). "Consequently, ANO9 promotes pancreatic cancer cell proliferation in vitro and in vivo." (PMID 36497413, 2022). "For instance, some key biomarkers have been exposed in pancreatic carcinoma, namely intercellular adhesion molecule 2 (ICAM2), anoctamin 9 (ANO9), proline-rich tyrosine kinase 2 (PYK2) and cyclin-dependent kinase 9 (CDK9)." (PMID 31412643, 2019).
colorectal cancer (5 papers, 2015 to 2022). A primary or metastatic malignant neoplasm that affects the colon or rectum. "TMEM16J/ANO9 was linked to pancreatic and colorectal cancer." (PMID 35207106, 2022). "ANO9 downregulation in colorectal cancer reportedly plays a role in tumorigenesis and cancer progression." (PMID 35207044, 2022). "Further, the ANO9 LG4 is significantly enriched for CNVs, SNPs and indels making it possible that an increase of site-specific mutagenesis could disrupt proper ANO9 regulation leading to the progression of late-stage colorectal cancer." (PMID 32383760, 2020). "This study aims to characterize the role and oncogenic mechanisms of ANO9 in stage II and III colorectal cancer (CRC)." (PMID 26317553, 2015).
tuberculosis (4 papers, 2016 to 2022). A chronic, recurrent infection caused by the bacterium Mycobacterium tuberculosis. "The ANO9 gene, also known as TMEM16J (anoctamin 9), together with the SIGIRR and the PKP3 genes constitute a polymorphic complex associated with susceptibility to tuberculosis." (PMID 31480266, 2019).
cervical cancer (1 paper, 2022). A primary or metastatic malignant neoplasm involving the cervix. "Overexpression of ANO4 or ANO9 in human cervical cancer cells (HeLa), enhanced constitutive shedding of the growth factor AREG and increased cell proliferation." (PMID 35207044, 2022).
metastatic cancer (1 paper, 2015). A carcinoma which has spread from the original site of growth to another anatomic site. "By use of a tissue microarray (75 cores) we investigated the protein expression of ANO9 in primary and metastatic cancer specimens and their matched nontumor counterparts." (PMID 26317553, 2015).
metastatic colorectal cancer (1 paper, 2020). "For example, overexpression of Anoctamin 9, ANO9, is associated with the progression of metastatic colorectal cancer." (PMID 32383760, 2020).
cancer (4 papers, 2015 to 2022). A tumor composed of atypical neoplastic, often pleomorphic cells that invade other tissues. "ANO9 mRNA expression was significantly associated with cancer recurrence and TNM stage." (PMID 26317553, 2015). "Taken together, in this study we showed that reduction of ANO9 has an important role in the tumorigenesis and cancer progression of stage II and III CRC." (PMID 26317553, 2015). "While ANO5, ANO7, and ANO9 may also be relevant for growth of cancers, evidence has been provided for a role of ANO6 (TMEM16F) in regulated cell death." (PMID 30893776, 2019). "Apart from ANO1, other members of the anoctamin family were also correlated with cell proliferation and cancer development, like ANO5 (TMEM16E), ANO7 (TMEM16G) and ANO9 (TMEM16J)." (PMID 30893776, 2019). "Especially, it induces MAPK and contributes directly to cancer progression, whereas ANO9 could inhibit the activity of ANO1 and other anoctamins, which implied that ANO9 might inhibit malignant progression." (PMID 26317553, 2015). "Although the exact function of ANO9 is still unclear, on the basis of present work, ANO9 plays a tumor-suppressor role in stage II and III CRC by inhibiting cell cycle, reducing proliferation, promoting apoptosis and decreasing cancer cell invasion." (PMID 26317553, 2015).
tumor (4 papers, 2015 to 2025). "In vitro functional studies showed that ANO9 contributed to tumor cell proliferation, apoptosis, and invasion." (PMID 26317553, 2015). "PcDNA3.1-vector cells showed about 3.61±0.37-fold and 1.64±0.19-fold penetration rate through the matrigel-coated membrane compared with PcDNA3.1-ANO9 in LoVo and HCT116 cells, respectively, which indicated that ANO9 reduced the invasion ability of tumor cells." (PMID 26317553, 2015). "Furthermore, we investigated the oncogenic mechanisms of ANO9 in human CRC cell lines, and found that it promotes cell proliferation and tumor invasion in vitro." (PMID 26317553, 2015).
kidney disease (2 papers, 2023 to 2025). "Notably, previous CKD genetic studies have seldom implicated ANO3, making our finding a novel insight, though related chloride channel genes such as ANO9 have been linked to kidney disease risk, highlighting the broader importance of electrolyte transport pathways." (PMID 41322097, 2025).
ANO9 also shares sentences with these, for which no sentence is quoted: chronic kidney disease (2 papers); autism (1); enterocolitis (1); esophageal squamous cell carcinoma (1); pneumonia (1).